PMS2 (PMS1 homolog 2, mismatch repair system component)
Diseases named in the same sentence as PMS2 in open-access papers (continued):
Sharing a sentence is not in itself a finding about the gene and the disease.
tumor (continued). "Paediatric-ALL was the only tumour type with somatic, relapse-associated PMS2 mutations." (PMID 39026103, 2024). "Tumor MLH1 methylation was detected in 23 tumors from 22 SLS cases where the concordance between the two internal assays was 100% and, in all but one of the tumors, there was loss of expression of MLH1 protein by IHC (a single MLH1 methylation positive tumor SLS005 showed solitary loss of PMS2)." (PMID 37101184, 2023). "Indeed, accumulating evidence suggests that PMS2-deficient (dPMS2) tumours show distinct biological behaviour that differs from other MMR-deficient (dMMR) cancers." (PMID 36895471, 2023). "Interestingly, molecular studies of the tumours revealed an ultra-mutated tumour phenotype with mutational signatures of both PMS2 and POLD1, suggesting that these factors interacted to cause the relatively severe clinical phenotype in these cases." (PMID 36895471, 2023). "In 16 patients, there was MLH1 ± PMS2 loss of expression in the tumor." (PMID 35954394, 2022). "If only poor quality DNA from FFPE tumor tissue was analysed, this variant may have been missed, which could also hold true for other (CN) variants in the notoriously difficult-to-analyse PMS2 gene." (PMID 36291559, 2022). "The patient’s tumor showed loss of MLH1/PMS2 expression and isolated loss of MSH6 expression." (PMID 36077770, 2022). "The tumor showed isolated PMS2 expression loss in neoplastic cells." (PMID 36291559, 2022). "In addition, both tumors have a high proportion of short-tandem-repeat variants, i.e., 27% and 23% for the brother’s and sister’s tumor, respectively, which is typical for (PMS2-associated) MSI tumors." (PMID 36291559, 2022). "There were 19.1% of samples that exhibited dMMR (MLH1/PMS2 loss), 70.6% of which had ≥ 1% PD-L1-positive tumor cells, compared to the proficient mismatch repair (pMMR) group, 56.9% of which showed ≥ 1% PD-L1-positive tumor cells (Spearman’s correlation coefficient(r) = 0.109, p = 0.412)." (PMID 36376881, 2022). "Eight tumors exhibited solitary MSH6 loss, while isolated PMS2 loss was observed in only one tumor." (PMID 33816285, 2021). "Interestingly, the variant appears to be associated with uncommon isolated loss of PMS2 protein expression in tumor tissue instead of MLH1 and PMS2 loss, which is usually seen with PVs in MLH1." (PMID 32197529, 2020). "Immunohistochemical analysis (IHC) also showed loss of the PMS2 protein in the tumor." (PMID 33193653, 2020).
tumor (continued). "Examples include mutations in RNF43 or PMS2, which could mark clonal subtypes that may make the tumor responsive to specific agents, such as checkpoint inhibitors." (PMID 31254442, 2019). "One patient with PMS2 tumour loss had a class 3 PMS2 variant (p.Glu705Lys)." (PMID 28466842, 2017). "The PMS2 N775L mutation was identified in both lymphocyte and tumor in this study." (PMID 28347324, 2017). "Therefore, the tumor exhibited both PMS2 and FOXL2 mutations, and PMS2 mutation occurred before FOXl2 mutation." (PMID 28347324, 2017). "Two patients had isolated tumor PMS2 loss (ages 68 and 86 years)." (PMID 28470797, 2017). "The splice mutation PMS2 c.989-1G > T met the InSiGHT criteria class 5 for pathogenicity: mRNA analysis showed that it caused two abnormal transcripts, it co-segregates with disease, more than 2 tumours were MSI-high and has a population frequency <1%." (PMID 24790682, 2014). "Several mutations in the PMS2 gene were identified among the patients with PMS2-deficient tumours." (PMID 24790682, 2014). "Nevertheless, heterozygosity of PMS2 in the present case as exhibited by c-DNA-sequencing might still be causally associated with the development of this exceedingly rare tumor." (PMID 21645337, 2011). "Additionally, the integration of tumor genomic data evaluating PMS2 somatic alterations in affected families’ members carrying the germline PMS2 Gly62Arg variant may also contribute to establishing its pathogenic role in LS." (PMID 40723192, 2025). "Tumor testing revealed microsatellite instability, loss of MLH1 and PMS2 expression, high tumor mutational burden (21.87 mutations/Mb), and wild‐type BRAF." (PMID 41347766, 2026). "In four patients, longitudinal analysis of subsequent lesions highlighted an increase in mutations, like missense or splice variants in the PMS2, SMARCA4, ARID1A, AKT1, BMPR1A, and PTEN genes, suggesting tumor evolution." (PMID 41514647, 2025). "PMS2-CMMRD cases were split into two distinct groups based on tumour onset age: early (diagnosis under 10 years) and later-onset (diagnosis after 10 years)." (PMID 41333974, 2025). "Limited data support the extension of surveillance intervals for carriers of pathogenic variants MSH6 and PMS2, who are proven to have lower cumulative CRC incidences, possibly due to this different tumour biology." (PMID 40241188, 2025).
tumor (continued). "MSI analysis revealed instability in BAT26 in the MLH1/PMS2-deficient tumor and at D17S250 in the MSH6-deficient tumor." (PMID 40415014, 2025). "Loss of MLH1 or both MLH1 and PMS2: When this pattern is observed, MLH1 promoter hypermethylation testing of tumor DNA is recommended." (PMID 40144212, 2025). "The pathological analysis confirmed a pT3N0M0, G3 stage II tumor, characterized by a loss of MLH1 and PMS2 protein expression, indicating microsatellite instability (MSI-H)." (PMID 40709126, 2025). "By analysing 133 cases and families with PMS2-associated CMMRD, we confirmed this characteristic pattern of tumor predisposition observed in the syndrome." (PMID 41333974, 2025). "The initial tumor was poorly differentiated adenocarcinoma, MLH1 and PMS2-deficient, and exhibited BRAF overexpression." (PMID 41170468, 2025). "In four patients, longitudinal analyses of subsequent lesions showed the maintenance of most genomic alterations and enrichment in missense or splice variants in PMS2, SMARCA4, ARID1A, AKT1, BMPR1A, and PTEN, indicating the occurrence of tumor evolution." (PMID 41514647, 2025). "Three patients were suspected to have cMMRD based on somatic tumor variants in the MLH1, MSH6, and PMS2 genes combined with the high mutational burden observed in their tumors." (PMID 40980447, 2025). "PRMT5 inhibition enhances CPT‐11 sensitivity, inducing a PMS2‐deficient‐like state and cytosolic dsDNA release, which activates the cGAS‐STING pathway to promote anti‐tumor immunity." (PMID 40344511, 2025). "The study revealed MSI tumours with MLH1/PMS2 defects and high-grade POLE-wildtype/MSS tumours expressing high immunogenicity characterized by intense T-cell infiltration, especially at the invasive edge." (PMID 41312167, 2025). "Approximately 25% of the tumor showed a deficiency in MLH1/PMS2 expression, with this area being clearly demarcated from the MLH1/PMS2-proficient region." (PMID 40076915, 2025). "Next generation sequencing of the tumor at baseline showed microsatellite instability high (loss of MLH1 and PMS2 and TMB 15, ARID1A G801FS*32, KRAS Q6H, PIK3CA N1044K, PTEN R130G, SMARCA4 P109FS*194 and SMARCA4 P316FS*10 mutations)." (PMID 40382524, 2025). "This chromosomal deletion causes the haploinsufficiency of several key tumor suppressors located on chromosome 7, such as EZH2, PMS2, HUS1, and NAMPT." (PMID 40981111, 2025). "In the dMMR population across all tumor types, protein loss of MLH1 and PMS2 in 68.6% (48/70) patients was observed most commonly." (PMID 41313676, 2025).
tumor (continued). "In a study of variant analysis by whole-genome or whole-exome sequencing of tumor samples from 175 EWS patients, other types of missense pathogenic variants of the PMS2 gene (c.137G > T; p.S46I) were also identified." (PMID 41514647, 2025). "This aspect is remarkable since in patients who carry MLH1 gene pathogenic variants, the somatic tumor hypermethylation of the MLH1 gene promoter is always associated with the loss of MLH1 and PMS2 proteins expression." (PMID 38732303, 2024). "Tumour screening analyses showed MSI-H in 5/7 tumours in carriers of this variant (ACMG criteria PP4_strong), while IHC showed normal staining for PMS2 protein in 7/7 tumours." (PMID 39334433, 2024). "In summary, this work demonstrated that somatic alterations of PMS2 contribute to brain metastases and provides compelling evidence that PMS2 upregulation is required for the tumor metastasizing to brain." (PMID 38714954, 2024). "Genetic testing showed a high tumor mutation burden (TMB-H, 42.24 mutations/Mb) with stable microsatellites and a suspected harmful mutation in the PMS2 gene." (PMID 39776912, 2024). "This work provides support for further exploration into the role of PMS2 in tumor development, and as a potential therapeutic mechanism." (PMID 39139583, 2024).
tumor (continued). "CRCs from MLH1: c.-11C > T VUS carriers had late diagnosis age, demonstrated loss of MLH1/PMS2 protein expression by IHC and showed MLH1 hypermethylation in the tumour concordantly by both loci-specific techniques and the HMEPIC data." (PMID 37270516, 2023). "PMS2 or MLH1 expression was lost in a higher fraction of the tumours, both in curettage (20.6% or 15.6%, respectively) and in hysterectomy samples (21.3% or 17.6%, respectively)." (PMID 36482191, 2023). "Immunostaining for the four MMR proteins confirmed loss of MLH1 and PMS2, and MSI molecular testing revealed that the tumor was indeed MSI-H, due to the alteration of three mononucleotide markers (BAT25, BAT26, Mono-27)." (PMID 36756361, 2023). "We also managed to produce a regression model for CDX2 expression and showed that poor tumor differentiation and MLH1/PMS2 heterodimer deficiency are independent factors for CDX2 expression loss." (PMID 37325467, 2023). "Tumor analysis displayed evidence for ALT and low mutational burden (0.6), PMS2 expression was retained, MSI was low." (PMID 37308967, 2023). "The patient's tumor showed an MSI phenotype and loss of MLH1 and PMS2 expression revealed by immunohistochemistry assay with negative MLH1 promoter hypermethylation." (PMID 37350751, 2023). "Somatically acquired biallelic MLH1 methylation in CRC results in loss of immunohistochemical expression of the MLH1 and PMS2 DNA mismatch repair (MMR) proteins and microsatellite instability within the tumour (i.e. MMR-deficiency)." (PMID 37270516, 2023). "According to our extensive literature research, we were the first to produce a regression model for CDX2 expression loss which showed that poor tumor differentiation and MLH1/PMS2 heterodimer deficiency are independent factors for CDX2 expression loss." (PMID 37325467, 2023). "PMS2-deficient CRC is unique since it is associated with fewer immune features, such as less pronounced CD3+ T cell infiltration in the tumour milieu." (PMID 36895471, 2023).